ABL1 (ABL proto-oncogene 1, non-receptor tyrosine kinase)
Diseases named in the same sentence as ABL1 in open-access papers (continued):
Sharing a sentence is not in itself a finding about the gene and the disease.
chronic myeloid leukemia (continued). "Chronic myelogenous leukaemia was the first human cancer to be associated with a consistent chromosomal abnormality, the Philadelphia chromosome, a translocation that juxtaposes the 3′ sequence from the ABL1 proto-oncogene on chromosome 9 with the 5′ sequence from the BCR gene on chromosome 22." (PMID 18665178, 2008). "(ABL1), first identified as the BCR–ABL1 fusion protein in patients with Philadelphia chromosome-positive human leukemia, has been the target of successful chronic myeloid leukemia therapeutics." (PMID 40346061, 2025). "Chronic myeloid leukemia (CML) is classified into three subtypes based on the BCR breakpoint, the rarest of which is micro BCR::ABL1 (also known as e19a2 BCR::ABL1), which encodes a P230 fusion protein." (PMID 40452681, 2025). "Chronic Myeloid Leukemia (CML) is characterized by the BCR::ABL1 fusion gene, driving uncontrolled myeloid cell proliferation." (PMID 40022557, 2025). "The primary etiological factor of chronic myeloid leukemia (CML) is the BCR::ABL1 fusion protein, which is a highly active tyrosine kinase capable of initiating multiple downstream oncogenic pathways." (PMID 40447744, 2025). "Explosive growth is attributed to the BCR::ABL1 gene 3–14 years before diagnosis of chronic myeloid leukaemia, highlighting the oncogenic potency of gene fusion and the slow and sequential trajectories of most other cancers." (PMID 40205062, 2025). "Chronic myeloid leukemia (CML) is a clonal malignancy propelled by the BCR::ABL1 fusion gene originating from the Philadelphia chromosome." (PMID 40893386, 2025). "BCR is classically associated with chronic myelogenous leukemia, in which it forms a fusion protein with tyrosine-protein kinase ABL1 (c-Abl) leading to aberrant kinase activity." (PMID 41035411, 2025). "Tyrosine kinase inhibitors (TKIs) targeting BCR::ABL1 have greatly improved the survival of patients with chronic myeloid leukemia (CML), and their teratogenicity appears as an important factor for individuals of childbearing potential." (PMID 40442861, 2025). "We report the case of a 51-year-old male patient initially diagnosed with JAK2-V617F-mutated polycythemia vera (PV), who developed chronic phase BCR::ABL1-positive chronic myeloid leukemia (CML) 11 years later." (PMID 41137901, 2025). "Chromosomal aberrations in ABL1 lead to fusion with the BCR gene, forming the oncogenic BCR-ABL1 complex, resulting in chronic myeloid leukemia." (PMID 40977267, 2025). "Breakpoint Cluster Region-Abelson (BCR::ABL1) fusion protein is essential in the pathogenesis of chronic myeloid leukemia (CML); however, the chronic-to-blast phase transformation remains elusive." (PMID 41502514, 2025). "Examples include acute myeloid leukemia (AML) with defining genetic alterations, BCR::ABL1-positive chronic myeloid leukemia (CML), or CCND1 rearrangements in mantle cell lymphoma (MCL)." (PMID 38769532, 2024). "A prominent, safe and efficient therapy for patients with chronic myeloid leukemia (CML) is inhibiting oncogenic protein BCR::ABL1 in a targeted manner with imatinib, a tyrosine kinase inhibitor." (PMID 39182842, 2024). "Targeted inhibition of oncogenic protein BCR::ABL1 with tyrosine kinase inhibitors (TKIs) is a front-line therapy in patients with chronic myeloid leukemia (CML) and Ph + acute lymphoblastic leukemia." (PMID 39182842, 2024). "Chronic myeloid leukemia (CML) is characterized by the constitutively active tyrosine kinase BCR::ABL1, and standard therapy is treatment with tyrosine kinase inhibitors (TKI)." (PMID 38278960, 2024). "The development of BCR::ABL1-targeting tyrosine kinase inhibitors (TKIs) has improved the prognosis of patients with chronic myeloid leukemia (CML)." (PMID 38714583, 2024). "These mutations are extensively studied in chronic myeloid leukemia (CML), compromise tyrosine kinase inhibitor (TKI) binding sterically, elimination of direct contacts and/or favoring an active conformation of the ABL1 KD." (PMID 39440695, 2024).
chronic myeloid leukemia (continued). "Chronic myeloid leukemia (CML) is a myeloproliferative neoplasm characterized by the expression of the BCR::ABL1 fusion protein, which exhibits constitutive tyrosine kinase activity." (PMID 38534885, 2024). "Patient 3 (P3) F/34Y was chronic myeloid leukaemia patient who presented in B-lymphoblastic crisis with another novel in-frame BCR::ABL1 fusion transcript." (PMID 38493200, 2024). "Chronic Myeloid Leukemia (CML) is a type of blood cancer characterized by the presence of the BCR::ABL1 fusion gene, commonly known as the Philadelphia chromosome." (PMID 38607055, 2024). "JAK inhibitors have not been able to eradicate neoplastic clones, as seen in targeted therapy with tyrosine kinase inhibitor (TKI) treatment for BCR::ABL1-positive chronic myeloid leukemia (CML)." (PMID 38339265, 2024). "To further challenge the scalability of μPhos, we also applied it to study time-resolved drug responses in murine pro-B lymphocyte Ba/F3 BCR::ABL1 positive cells, a pre-clinical model of chronic myeloid leukemia (CML)." (PMID 38907068, 2024). "KEGG pathway analysis revealed that four hub genes- ABL1, HDAC1, HDAC2 and MDM2 - were primarily associated with chronic myeloid leukemia (KEGG:05220 and P = 3.27E-08) and notch signaling pathway (KEGG:04330 and P = 2.38E-04)." (PMID 38832038, 2024). "We set a target candidate profile (TCP) objective with affinity, lipophilicity, and solubility goals for a hypothetical hit-to-lead phase of a discovery program against ABL1, a kinase dysregulated in cancers such as chronic myelogenous leukemia." (PMID 38854082, 2024). "The introduction of ABL1 tyrosine kinase inhibitors (TKIs) has improved survival outcomes for patients with chronic phase chronic myeloid leukemia (CML-CP) markedly." (PMID 39136895, 2024). "We describe the case of a chronic myeloid leukemia (CML) patient with a rare atypical e18a2 BCR::ABL1 transcript." (PMID 39624635, 2024). "Tyrosine kinase inhibitors (TKIs) inhibit the disease-defining BCR::ABL1 fusion kinase, are highly effective for chronic myeloid leukemia (CML), and have revolutionized its treatment." (PMID 38776875, 2024). "The introduction of imatinib and the following second generation tyrosine kinase inhibitors (TKIs) dasatinib and nilotinib, targeting the pathognomonic BCR::ABL1 fusion protein, has revolutionized chronic myeloid leukemia (CML) treatment." (PMID 36602564, 2023). "Two main groups of MPN, BCR::ABL1-positive (Chronic Myeloid Leukemia) and BCR::ABL1-negative (Polycythemia Vera, Essential Thrombocytosis, Primary Myelofibrosis) are distinguished." (PMID 36980287, 2023). "Chronic myeloid leukemia (CML) is characterized by a massive expansion of predominately myeloid lineage cells driven by the constitutively active BCR::ABL1 fusion tyrosine kinase." (PMID 37932786, 2023). "Research has indicated that the SH3 domain of the ABL1 protein negatively regulates its function, and high expression of ABL1 often indicates poor prognosis, which is commonly observed in chronic myeloid leukemia, but it is less studied in other cancers." (PMID 38145160, 2023). "Imatinib targets the BCR::ABL1 fusion gene and inhibits Abelson tyrosine kinase, making it widely used to treat chronic myeloid leukemia (CML)." (PMID 37837401, 2023). "BCR::ABL1 fusion has significant prognostic value and is screened for chronic myeloid leukemia (CML) disease monitoring as a part of routine molecular testing." (PMID 37248544, 2023). "Tyrosine kinase inhibitors (TKI) are effective target-specific inhibitors of the constitutively active BCR::ABL1 oncoprotein characterizing chronic myeloid leukemia (CML)." (PMID 37875583, 2023). "Chronic myeloid leukemia (CML) is characterized by the presence of a BCR::ABL1 fusion gene on the Philadelphia chromosome." (PMID 38034530, 2023).
chronic myeloid leukemia (continued). "Although the development of BCR::ABL1 tyrosine kinase inhibitors (TKIs) rendered chronic myeloid leukemia (CML) a manageable condition, acquisition of drug resistance during blast phase (BP) progression remains a critical challenge." (PMID 37932786, 2023). "Chronic Myeloid Leukemia (CML) is a commonly occurring hematological neoplasm, in adults, caused by BCR::ABL1 gene mutation in the myeloid cells." (PMID 38188307, 2023). "The development of BCR::ABL1 tyrosine kinase inhibitors (TKIs), such as dasatinib, has dramatically improved survival in cases of chronic myeloid leukaemia (CML)." (PMID 36847709, 2023). "Although mutant ABL1 is known to have oncogenic role, the normal ABL1 was shown to have tumor suppressor function in chronic myeloid leukemia model." (PMID 37533202, 2023). "Chronic myeloid leukemia (CML) is a hematologic neoplasm characterized by the expression of the BCR::ABL1 oncoprotein, a constitutively active tyrosine kinase, resulting in uncontrolled growth and proliferation of cells in the myeloid lineage." (PMID 38004514, 2023). "Over the past two decades, three generations of Tyrosine Kinase Inhibitors (TKIs) have been developed to target the BCR::ABL1 oncoprotein to successfully treat chronic myeloid leukemia (CML)." (PMID 36765952, 2023). "Response to tyrosine kinase inhibitor (TKI) therapy in patients with chronic myeloid leukemia (CML) is monitored by quantification of BCR::ABL1 transcript levels." (PMID 37875583, 2023). "Chronic myeloid leukemia results from the abnormal activation of ABL1 kinase due to a chromosomal translocation." (PMID 37895484, 2023). "Those falling within the major breakpoint cluster region (M-bcr) yield the common 210 kDa fusion protein (P210BCR::ABL1) which is highly specific for chronic myeloid leukaemia." (PMID 37496024, 2023). "Chronic myelogenous leukemia is characterized by presence of the BCR:ABL1 fusion and treated using imatinib mesylate (Gleevec)." (PMID 35625354, 2022). "Considerably, ABL1 is a molecular target for both Imatinib (treating chronic myeloid leukemia) and Mesylate which is in phase I clinical trial for endometrial cancer." (PMID 36704357, 2022). "In most patients with chronic myeloid leukemia (CML) clonal cells can be kept under control by BCR::ABL1 tyrosine kinase inhibitors (TKI)." (PMID 35794848, 2022). "Imatinib is a first-line therapy for chronic myeloid leukemia (CML), a form of cancer caused by chromosomal fusion of BCR and ABL1." (PMID 36090793, 2022). "The third-generation tyrosine kinase inhibitor DCC-2036 (Rebastinib), designed as an inhibitor of ABL1 switch-control, is powerful in chronic myeloid leukemia (CML)." (PMID 36042208, 2022). "Tyrosine kinase inhibitors (TKIs) targeting BCR::ABL1 have turned chronic myeloid leukaemia (CML) from a fatal disease into a manageable condition for most patients." (PMID 36536477, 2022). "We analyzed BCR::ABL1 expression at stop and in the first month after discontinuation in 168 chronic myeloid leukemia patients who stopped imatinib or 2nd generation tyrosine kinase inhibitors (2G-TKIs) while in sustained deep molecular response." (PMID 36208021, 2022). "Apart from its established role in chronic myeloid leukemia, studies have also suggested that amplification or overexpression of Abl1 and Abl2 is related to different carcinomas and related to solid tumors." (PMID 34840927, 2021). "For example, in the BCR-ABL1 fusion gene product, which is commonly found in chronic myeloid leukemia, ABL1 tyrosine kinase is constitutively activated even in the absence of growth-stimulating signals." (PMID 34440406, 2021). "Chronic myeloid leukemia (CML) is a myeloproliferative neoplasm characterized by the Philadelphia chromosome which is the source of a Bcr-Abl1 hybrid protein with constitutive tyrosine-kinase activity." (PMID 34660261, 2021).
chronic myeloid leukemia (continued). "Chronic myeloid leukemia (CML) is featured by the chromosomal translocation of 22q1 with 9q34 to produce a BCR/ABL1 fusion gene." (PMID 34781898, 2021). "The constitutively active tyrosine-kinase BCR/ABL1 oncogene plays a key role in human chronic myeloid leukemia development and disease maintenance, and determines most of the features of this leukemia." (PMID 33557401, 2021). "The promise of targeted therapies in cancer was first realized with the discovery of the fusion between BCR (breakpoint cluster region gene) and ABL1 (Abelson tyrosine-protein kinase 1) genes in chronic myelogenous leukemia (CML) patients." (PMID 34461089, 2021). "ABL1 on chromosome 9 undergoes mutual translocation with the BCR gene on chromosome 22 to make the Philadelphia chromosome, which is well known to cause chronic myelogenous leukemia." (PMID 33952249, 2021). "Kinase inhibitors, most notably those targeting ABeLson 1 (ABL1) kinase in chronic myeloid leukemia, have had a significant impact on cancer survival, yet emergence of resistance mutations can reduce their effectiveness, leading to therapeutic failure." (PMID 34667533, 2021). "Chronic myeloid leukemia is a hematologic malignancy associated with the fusion of two genes: BCR and ABL1." (PMID 34030730, 2021). "Inhibiting ABL1 with tyrosine kinase inhibitors (TKIs), which is used for chronic myelogenous leukemia (CML), reduced the proviral load (PVL) in vitro." (PMID 32667912, 2020). "Chronic myeloid leukemia (CML) is characterized by the expression of the BCR/ABL1 fusion gene and the presence of the Philadelphia chromosome (Ph)." (PMID 33102599, 2020). "Imatinib (Gleevec), an inhibitor that blocks the BCR-Abelson murine leukemia viral oncogene homolog 1 (ABL1) tyrosine kinase activated in chronic myeloid leukemia (CML), is an outstanding example of an effective targeted therapy." (PMID 35582276, 2019). "One of the first malignancies where targeted therapies proved effective was chronic myeloid leukaemia (CML) that involves the constitutively active tyrosine kinase Abl1." (PMID 31138173, 2019). "Targeted inhibition of the oncogenic BCR-ABL1 fusion protein using the ABL1 tyrosine kinase inhibitor imatinib has become standard therapy for chronic myelogenous leukemia (CML), with most patients reaching total and durable remission." (PMID 28678800, 2017). "Imatinib mesylate (Gleevec) inhibits Abl1, c-Kit, and related protein tyrosine kinases (PTKs) and serves as a therapeutic for chronic myelogenous leukemia and gastrointestinal stromal tumors." (PMID 25822986, 2015). "While ABL1 has been relatively unexplored in AML, it has been implied for association with the resistance of chemotherapy in chronic myeloid leukemia." (PMID 26517675, 2015). "During the past decade, the tyrosine kinase inhibitor (TKI) imatinib has been successfully used for the treatment of patients with BCR/ABL1+ chronic myeloid leukemia (CML) and for the treatment of FIP1L1/PDGFRA+ chronic eosinophilic leukemia (CEL)." (PMID 25605011, 2015). "The BCR/ABL1 fusion is a well-studied entity, present in all the cases of Chronic Myeloid Leukemia (CML) and approximately 20% cases of B-cell ALL." (PMID 26600955, 2015). "A classic example of oncogenic fusions is BCR-ABL1 in chronic myelogenous leukemia, which is generated by a translocation between chromosomes 9 and 22, and exhibits constitutive ABL1 tyrosine kinase activity." (PMID 24727804, 2014). "Gene fusions, like BCR/ABL1 in chronic myelogenous leukemia, have long been recognized in hematologic and mesenchymal malignancies." (PMID 23637631, 2013).
chronic myeloid leukemia (continued). "Asciminib represents a significant advancement in the treatment of chronic myeloid leukemia, establishing a novel therapeutic paradigm by specifically targeting the ABL1 myristoyl pocket, a mechanism distinct from that of conventional adenosine triphosphate-competitive inhibitors." (PMID 41724089, 2026). "Using BCR::ABL1 monitoring in chronic myeloid leukemia as a case study, we aligned measurements to 90-day intervals, applied a windowed, uncertainty-propagating imputation strategy, and trained recurrent neural network (RNN) and XGBoost models to forecast values three and six months ahead." (PMID 41542066, 2026). "In 2001, imatinib, the first-in-class tyrosine kinase inhibitor (TKI), was approved by the Food and Drug Administration (FDA) for treatment of mutated BCR-ABL (breakpoint cluster region (BCR) and abelson murine leukemia viral oncogene homolog 1 (ABL1)) chronic myeloid leukemia (CML)." (PMID 41402855, 2025). "Data on FR expression in BCR::ABL1-positive chronic myeloid leukemia (CML) is scarce." (PMID 39847116, 2025). "The BCR::ABL1 fusion gene is the primary molecular marker of chronic myeloid leukemia (CML)." (PMID 40166069, 2025). "In this view, we assumed that any kind of treatment administered before a confirmed diagnosis of chronic myeloid leukemia might change the amount of BCR::ABL1 transcript levels." (PMID 40076467, 2025). "Chronic myeloid leukemia (CML) is a hematopoietic malignancy driven by the fusion gene BCR::ABL1." (PMID 37880985, 2024). "Asciminib is a first-in-class allosteric BCR::ABL1 inhibitor and was recently approved for the treatment of adults with Philadelphia (Ph) chromosome-positive chronic myeloid leukaemia (CML) in chronic phase, who have previously been treated with two or more tyrosine kinase inhibitors (TKIs)." (PMID 38879610, 2024). "Chronic myeloid leukemia (CML) is characterized by a reciprocal translocation between chromosome 9 and 22 in the hematopoietic stem cell that results in formation of the Philadelphia chromosome (Ph), encoding the BCR::ABL1 fusion gene." (PMID 38965368, 2024). "Chronic myeloid leukaemia (CML) represents the only BCR::ABL1-positive MPN." (PMID 38835971, 2024). "Chronic myeloid leukemia (CML) represents about 20% of all adult leukemia cases and is caused by a chromosomal translocation between chromosomes 9 and 22, leading to the expression of the fusion kinase BCR::ABL1." (PMID 37161070, 2023). "Similarly, the ICC uses a 10% blast cutoff for most molecularly defined subtypes of AML, again with the exception of BCR::ABL1 to avoid confusion with the diagnosis of chronic myeloid leukemia (CML)." (PMID 36966300, 2023). "Chronic myeloid leukemia was induced in the tol2 system by introducing human BCR/ABL1 oncogenes." (PMID 36142160, 2022). "Although high expression occurs mainly in chronic myelogenous leukemia by translocation of ABL1, it has recently been reported that the ABL1 gene may have an effect on the onset of solid cancer." (PMID 33952249, 2021). "ABL1 presents at 9q34.12 on chromosome 9, translocate with the breakpoint cluster region (BCR) gene on chromosome 22 to form the Philadelphia chromosome, the cause of chronic myelogenous leukemia." (PMID 33952249, 2021). "Oncogenic forms of ABL1, in particular the BCR-ABL1 fusion gene with different breakpoints in BCR gene, are well-recognized for their pathogenic role in leukemias, including chronic myeloid leukemia (CML), some forms of acute myeloid leukemia (AML), and acute lymphoblastic leukemia (ALL)." (PMID 34867354, 2021). "Chronic myeloid leukemia (CML) is a myeloproliferative neoplasm characterized by the presence of the Philadelphia chromosome that encodes for the tyrosine kinase protein BCR-ABL1 from the Breakpoint Cluster Region (BCR) sequence and the Abelson (ABL1) gene." (PMID 33466839, 2021).